TERT (telomerase reverse transcriptase)
Diseases named in the same sentence as TERT in open-access papers (continued):
Sharing a sentence is not in itself a finding about the gene and the disease.
oligodendroglioma (117 papers, 2014 to 2026). A well-differentiated (WHO grade II), diffusely infiltrating neuroglial tumor, typically located in the cerebral hemispheres. "Recurrent molecular genetic alterations, such as IDH1/2, FUBP1, CIC, and TERT promoter mutations, have been identified to co-occur with 1p/19q co-deletion in oligodendrogliomas." (PMID 40426960, 2025). "TERT promoter mutations are frequently observed in glioblastomas (70~80%) and oligodendrogliomas (60~70%)." (PMID 40426960, 2025). "Oligodendrogliomas are well known to be mutated for TERT promoter (TERTp), which is enigmatically a diagnostic criterion for molecular glioblastoma by the World Health Organization (WHO) 2021 classification." (PMID 38371225, 2024). "Other alterations characteristic of oligodendrogliomas are TERT promoter and CIC, FUBP1, and NOTCH1 mutations." (PMID 37239289, 2023). "IDH-wildtype GBM demonstrates alterations in epidermal growth factor receptor (EGFR), and similar to oligodendrogliomas, exhibit TERT promoter mutations." (PMID 37274223, 2023). "Numerous differences, however, were apparent, including increased TMB-high and dMMR/MSI-H prevalence in GBM, and a high rate of TERT promoter mutation and 1p19q codeletion in oligodendroglioma." (PMID 37291277, 2023). "The TERT promoter mutation (chr5:1,295,113:C>T, C228T), found in the majority of oligodendrogliomas, was also detected in all four tumors (VAF Case 1: 0.60 and 0.64, Case 2: 0.33 and 0.38 for primary and relapsed samples, respectively)." (PMID 35982066, 2022). "The case of RAS-mutant anaplastic oligodendroglioma showed IDH1 and TERT promoter mutations, which are known to be detected in almost all oligodendrogliomas." (PMID 34525976, 2021). "The group with mutations in both IDH and TERT (Group C) mainly consisted of oligodendroglioma (OL) or anaplastic oligodendrogliom (AO) (85.8%)." (PMID 34814870, 2021). "LGGs with an IDH1 mutation and 1p19q co-deletion show oligodendroglioma histological characteristics and arise from TERT activation, mutations in CIC and FUBP1, and activating alterations in the phosphoinositide-3-kinase (PI3K) pathway." (PMID 32120790, 2020). "In oligodendrogliomas, a variant in the TERT promoter was found in 78% of cases (n = 45), and of these, 43% were the C250T variant." (PMID 31217899, 2019). "TCF12 mutations occurred only among oligodendrogliomas 1p19q codeleted with TERT promoter mutations and with IDH1 or IDH2 mutations (particularly frequent among IDH2-mutated tumors)." (PMID 30279357, 2018). "IDH, TERT co-mutated oligodendrogliomas showed the most favorable prognosis followed by IDH-mutant astrocytomas only." (PMID 30082856, 2018). "Three types of molecular subtypes were identified: IDH1/2-mutant (IDH-mutant astrocytomas), IDH1/2-mutant with TERT promoter mutation (IDH, TERT co-mutated oligodendrogliomas), and IDH-wild type (IDH-wildtype astrocytomas)." (PMID 30082856, 2018). "Case 4, a 57-year-old man, was diagnosed with Grade II, IDH mutant oligodendroglioma, featuring TERT mutation and 1p19q co-deletion (Case 4)." (PMID 28660218, 2017). "Mutations in the TERT promoter are present in ~80% of oligodendrogliomas and are mutually exclusive of ATRX mutations commonly seen in non-oligodendroglial lower grade gliomas." (PMID 28388591, 2017). "For example, 1p/19q co-deletion, IDH1/2 and TERT promoter mutation are oligodendroglioma defining alterations." (PMID 28388591, 2017). "In the oligodendroglioma case, which featured TERT mutation, IDH1 mutation, and 1p19q co-deletion, high levels of tracer uptake were found in both PET studies (Case 4)." (PMID 28660218, 2017).
oligodendroglioma (continued). "Previous reports also demonstrated slightly less than 100% incidence of TERT promoter mutation in 1p/19q-codeleted oligodendrogliomas." (PMID 28270234, 2017). "The TERT promoter mutations almost always coincide with IDH mutations and 1p/19q codeletion in oligodendrogliomas, whereas a combination of TERT mutation and wild-type IDH is the most common genotype observed in GBM." (PMID 27503138, 2016). "The group with mutations in both IDH and TERT (Group A) mainly consisted of oligodendrogliomas or oligoastrocytomas (82 %)." (PMID 27503138, 2016). "The frequency of TERT promoter mutations in an additional cohort of 63 oligodendroglioma was 54% (34/63), confirming earlier observations of lower frequency in a less malignant brain tumor subtype." (PMID 26143636, 2015). "As a secondary analysis, the 69 oligodendrogliomas with 1p/19q status available were analyzed for an association with TERT promoter/IDH1/2 mutational status." (PMID 24722048, 2014). "TERT promoter mutations were also common in oligodendrogliomas (79.3%); however, TERT promoter mutations were less frequently identified in Grade II-III astrocytomas (18.2%, 16/88)." (PMID 24722048, 2014). "Grade II-III oligodendrogliomas have frequent co-occurring mutations in the TERT promoter and IDH1/2." (PMID 24722048, 2014). "Tumors harboring mutations typically seen in oligodendroglioma (both TERT promoter and IDH1/2 mutation) had a more favorable prognosis (median 125.2 months)." (PMID 24722048, 2014). "We provide evidence that over 86% of oligoastrocytomas in this cohort contain genetic signatures representative of either astrocytoma (IDH1/2 mutations alone) or oligodendroglioma (TERT promoter/IDH1/2), signatures that we show are associated with OS." (PMID 24722048, 2014). "TERT promoter mutations are frequent in primary GBMs and oligodendrogliomas but uncommon in lower grade astrocytoma." (PMID 24722048, 2014). "Oligodendrogliomas were almost exclusively TERT promoter and IDH1/2 mutated (79.3%, 69/87), but a fraction, 17.2% (15/87) harbored mutations in IDH1/2 alone." (PMID 24722048, 2014). "Sanger sequencing of the TERT promoter region was performed (i) for all WGS samples having only low coverage in the promoter sequence (below 40×, n = 6), (ii) the FFPE extension cohort, and (iii) three oligodendrogliomas, known to carry high frequency TERT promoter mutation." (PMID 35538064, 2022). "Notably, ATRX (X-linked nuclear protein) mutations are rare in oligodendrogliomas and are mutually exclusive with TERT since both these two genes target the lengthening telomeres." (PMID 35875065, 2022). "Therefore, a more biologically informative and clinically relevant oligodendroglioma model would be introducing the 1p/19q co-deletion and other coordinating mutations (eg, TERT promoter, and FUBP1 or CIC) in IDH mutant cells of the oligodendrocytic lineage." (PMID 36225650, 2022). "Moreover, in oligodendrogliomas, patients in the TERT-wildtype group had significantly worse OS than those in the TERT-mutated group." (PMID 34638714, 2021). "Additionally, we found that the expression of RBPs in GBMs with TERT mutation was significantly higher than that of oligodendrogliomas with TERT mutation." (PMID 32272554, 2020). "The overall number of variants (n = 82 - including TERT) in recurrent O2010 was significantly higher compared to primary O2005 (n = 12 - including TERT) and the average for primary oligodendrogliomas, but was consistent with cases from patients who had undergone treatment." (PMID 31217899, 2019).
oligodendroglioma (continued). "A novel TERT-targeting therapy would be expected to specifically target IDH-wildtype GBM including primary brain tumor initiating cells and 1p/19q-codeleted oligodendroglioma which have characteristically possessed hotspot mutations in the TERT promoter region." (PMID 29693015, 2018). "Another group studied the mutation fraction using multisector sequencing in 1p/19q-codeleted oligodendrogliomas and found that TERT promoter mutations indeed are early events and may occur before IDH mutations." (PMID 29616301, 2018). "This was because more detailed information was thought necessary to discriminate IDH-mutant astrocytomas from IDH and TERT co-mutated oligodendrogliomas, however, losing location information related to the deep white matter by abandoning “MNI structural atlas”." (PMID 30082856, 2018). "IDH, TERT co-mutated oligodendrogliomas preferably involved the frontal lobe." (PMID 30082856, 2018). "The remaining case was originally classified as a mixed oligo-astrocytoma, which, by virtue of the presence of IDH1_R132 and TERT promoter mutation (C228T), as well as copy-number loss of chromosomes 1p and 19q, would be described as an oligodendroglioma according to WHO 2016." (PMID 29763623, 2018). "Therefore, mutations other than IDH1 and 1p/19q-codeletion including TERT promoter mutation appear to be later events in oligodendroglioma oncogenesis." (PMID 28270234, 2017). "Furthermore, the recent identification of IDH1, CIC and TERT mutations will lead to new models that should give more insights into the mechanisms of oligodendroglioma genesis." (PMID 25008045, 2014). "In oligodendrogliomas, TERT promoter and IDH1/2 mutations co-occurred in 79% of cases." (PMID 24722048, 2014). "Oligodendrogliomas are characterized by IDH1/2 mutations in combination with complete 1p/19q codeletion, often with TERT promoter mutations and CIC/FUBP1 alterations, which results in a favorable prognosis and chemosensitivity." (PMID 41596318, 2026). "1p/19q co-deletion was detected by fluorescence in situ hybridization (FISH) and Tempus xT 648 gene panel reported genomic variants in IDH1, TERT, CIC, and FUBP1, as expected for an oligodendroglioma." (PMID 39857783, 2025). "TERT: Oligodendrogliomas have loss of one copy of the entire short arm of chromosome 1 (1p) along with one copy of the long arm of chromosome 19 (19q) by definition and may harbor TERT activating promoter mutations which are early and clonal events in gliomagenesis." (PMID 40949165, 2025). "Genetic mutations of the telomerase reverse transcriptase (TERT) promoter region do not co-exist with IDH1 mutations in primary GBMs; however, co-mutations in TERT promoter and IDH1/2 are often detected in oligodendrogliomas, which indicates a good prognosis." (PMID 37092846, 2023). "TERT mutations have been reported to be closely associated with IDH1/2 mutations and 1p/19q-codeletion in oligodendroglioma, but less well correlated in astrocytomas." (PMID 36831683, 2023).
oligodendroglioma (continued). "In adults, oligodendrogliomas with IDH mutation and 1p/19q-codeletion also present with mutations in the TERT promoter gene." (PMID 37274223, 2023). "A hotspot TERT promoter mutation was detected in 11/13 samples, 5/13 samples had a FUBP1 mutation, 4/13 samples a CIC mutation similar to conventional oligodendrogliomas." (PMID 34967922, 2022). "Twenty-nine of these (corresponding to oligodendrogliomas) harbored a concomitant 1p/19q co-deletion, and all of them except three were also TERT promoter mutant." (PMID 34558656, 2022). "In IDH-mutant and 1p/19q-codeleted oligodendrogliomas, we found that IDH mutation, TERT promoter mutation, and 1p/19q codeletion are clonal alterations in the vast majority of tumors." (PMID 35361262, 2022). "We exemplified this by comparing mutant allele frequencies of IDH1 or IDH2 and the TERT promoter, as well as deleted allele frequencies on 1p and 19q in a cohort of 20 IDH-mutant and 1p/19q-codeleted oligodendrogliomas." (PMID 35361262, 2022). "Oligodendrogliomas were characterized by a common 1p/19q deletion and mutations in CIC, FUBP1, Notch1, and TERT promoters." (PMID 35572524, 2022). "It has been shown that LGG patients with IDH mutations accompanying 1p19q deletions have features of oligodendrogliomas, 62% have CIC mutations, and 96% will carry TERT promoter mutations." (PMID 36589241, 2022). "Most tumors including low-grade oligodendrogliomas use telomerase reverse transcriptase (TERT) expression for telomere maintenance while astrocytomas use the alternative lengthening of telomeres (ALT) pathway." (PMID 33397920, 2021). "Further molecular studies identified mutations in TERT (telomerase reverse transcriptase), FUBP1 (far upstream element-binding protein 1), and CIC (capicua transcriptional repressor) in oligodendrogliomas." (PMID 32444979, 2020). "Astrocyte subpopulation gene signatures (PopD, PopE, Cortex, and PopA cortex) clustered a subset of LGG samples into oligodendrogliomas with IDH mutation and 1p/19q codeletion, TERT promoter mutations, and CIC gene mutations." (PMID 30957015, 2019). "A brain tumor which contains isocitrate dehydrogenase (IDH) and telomerase reverse transcriptase (TERT) mutation, accompanied with 1p/19q deletion would be diagnosed as an oligodendroglioma; IDH mutation with wild TERT is a characteristic of astrocytoma." (PMID 31708732, 2019). "We also noted that the medial frontal cortex was a location specific for IDH1/2-mutant with TERT promoter mutant oligodendrogliomas." (PMID 30082856, 2018). "Oligodendrogliomas, IDH-mutant and 1p/19q-codeleted almost universally use telomerase to maintain telomeres and virtually all of these tumors carry an activating TERT promoter mutation." (PMID 29616301, 2018). "Frequently occurring driver mutations in oligodendrogliomas include mutations in IDH1, CIC, FUBP1, TERT promoter and NOTCH." (PMID 25694352, 2015). "A meta-analysis including 9411 cases and 13708 controls showed that TERT rs2736100 was significantly associated to GBM also to astrocytoma and oligodendroglioma." (PMID 26143636, 2015). "A minor fraction of GBMs (0.8%, 2/240) contained mutations in both the TERT promoter and IDH1/2 suggesting they were treated oligodendrogliomas that were diagnosed as small cell GBMs." (PMID 24722048, 2014). "More recently, mutations within the core promoter of telomerase reverse transcriptase (TERT) have been found in 100 % of oligodendrogliomas with 1p19q codeletion and exclusively in this group of tumors." (PMID 25008045, 2014).
oligodendroglioma (continued). "In oligodendrogliomas, TERT mutations are linked to a poor prognosis in the absence of IDH mutations." (PMID 40546613, 2025). "Oligodendroglioma is molecularly defined by the presence of the isocitrate dehydrogenase 1 (IDH1) (most commonly IDH1 p.R132H) or IDH2 mutations and 1p/19q codeletion, frequently with an additional Telomerase Reverse Transcriptase (TERT) promoter mutation." (PMID 39061087, 2024). "Mutations in the promoter region of TERT are common driver events in oligodendrogliomas, but they were not detectable due to the limitations of exome sequencing." (PMID 37533228, 2023). "Among all adult-type diffuse gliomas combined, the optimal driver mutation VAF (either TERT for IDHwt GBM or IDH1/2 for IDHmut astrocytoma and IDHmut oligodendroglioma) in the context of MGMT promoter methylation pyrosequencing was determined by Cutoff Finder at 0.325." (PMID 37919784, 2023). "Three of the 20 oligodendrogliomas were TERT promoter wildtype." (PMID 35361262, 2022). "Moreover, nearly all 1p-19q codeleted oligodendrogliomas bear an IDH1/2 mutation, along with Telomerase Reverse Transcriptase (TERT) promoter mutation and MGMT gene methylation." (PMID 35806153, 2022). "Although ultimately it is the accumulation of genetic events that results in cancer, the putative timeline of our oligodendroglioma might provide insight for the contribution of IDH, TERT and 1p/19 codeletion to the development of oligodendroglioma." (PMID 31217899, 2019). "Concurrent mutations of TERT and IDH predict good prognosis, as an alternative hallmark of oligodendroglioma, whereas TERT promoter mutation with wild-type IDH tends to be associated with poor prognosis, although its use in predicting outcomes in GBM is controversial." (PMID 27503138, 2016). "Based on the available data, ‘canonical oligodendroglioma’ in adult patients could be defined as a diffuse glioma with complete 1p/19q codeletion, most of which will also have an IDH and a TERT mutation." (PMID 25943885, 2015). "However, in oligodendrogliomas, the TERT promoter mutation always occurred in the setting of the IDH1/2 mutation, which is frequent in both oligodendrogliomas and astrocytomas." (PMID 24722048, 2014). "GBMs were characterized as primarily TERT promoter mutant/IDH wildtype (73.3%), Grade II-III astrocytomas were predominantly TERT promoter wildtype/IDH mutant (73.9%), and the majority of oligodendrogliomas mainly harbored mutations in both the TERT promoter and IDH1/2 (79.3%)." (PMID 24722048, 2014). "However, it misses oligodendroglioma important pathogenic variants in p-TERT, CIC, FUBP, and NOTCH1." (PMID 37908227, 2023). "In the present study, we excluded patients with oligodendroglioma, or those with IDH mutated- TERT promoter mutated, or both because oligodendroglioma is considered to show better prognosis than astrocytoma and is often accompanied by both IDH and TERT promoter mutations." (PMID 35017570, 2022). "In our cohort, no oligodendroglioma cases harbored TERT promoter mutations alone." (PMID 24722048, 2014). "Similarly, younger patients with oligodendroglioma had 1p/19q codeletion without TERT mutations." (PMID 40949165, 2025). "We found that the slopes were maximally different at subtype-specific VAF inflection points: TERT VAF = 0.18 for IDHwt GBM, IDH VAF = 0.325 for IDHmut astrocytoma, and IDH VAF = 0.30 for IDHmut oligodendroglioma (respectively)." (PMID 37919784, 2023). "Telomerase reverse transcriptase (TERT) has been shown to be essential for tumor proliferation, including in low-grade oligodendrogliomas (LGOGs)." (PMID 35262263, 2023).